UCA1 (urothelial cancer associated 1)
Diseases named in the same sentence as UCA1 in open-access papers (continued):
Sharing a sentence is not in itself a finding about the gene and the disease.
tumor (continued). "UCA1 involved in tumor proliferation, invasion, migration and apoptosis, and played an important role in tumor progression, metastasis and prognosis." (PMID 30918102, 2019). "A total of 90 patients with LSCC and 90 healthy subjects were enrolled in order to evaluate levels of UCA1 in tumor tissues and adjacent healthy tissues, as well as serum." (PMID 31336999, 2019). "After analyzing the UCA1 level in 40 paired GC and adjacent non-tumor tissue samples, we found that UCA1 especially overexpressed in intestinal GC tissues." (PMID 31272462, 2019). "The effects of UCA1 overexpression on in vivo tumor growth were assess in a xenograft nude mice model." (PMID 31596734, 2019). "The western blot results in LV-sh-UCA1 revealed that CLOCK expression was suppressed in tumor tissues." (PMID 31798345, 2019). "As key targets of miR-122-5p, IGF-1R and PKM2 have been reported to promote tumor growth and metastasis, indicating the functional similarity of UCA1." (PMID 29669595, 2018). "Previous data showed that UCA1 plays a tumor suppressor role by reducing the expression level of c-Myc in esophageal squamous cell carcinoma." (PMID 30134946, 2018). "Extrapolating the role of UCA1 in different cancer cells to CRC cells suggests a role for UCA1 in cell cycle progression and cell proliferation, which is highly relevant to tumor growth." (PMID 30441811, 2018). "This opposite deregulation would suggest that the oncogenic function of UCA1 is crucial for tumor progression, inducing tumor cells to retain the lncRNA by limiting its secretion through exosomes." (PMID 30195762, 2018). "As expected, the TCGA GC cohort demonstrated that UCA1 presented the same trend in GC tissues and non-tumor tissues (P < 0.001)." (PMID 30464170, 2018). "In summary, this is the first demonstration that exosomal UCA1 has the key characteristics of a tumor marker: it can be assayed in a noninvasive manner, and it is relatively abundant and stable." (PMID 30377411, 2018). "Since then, emerging lncRNAs such as MALAT1, TUG1, and UCA1 had been demonstrated to be tumor markers or prognostic indicators of BC26." (PMID 29445179, 2018). "Urothelial carcinoma-associated 1 (UCA1) was reported to be markedly upregulated in HCC tissues and its expression in HCC is positively associated with tumor size, vascular invasion, TNM stage, metastasis, and postoperative survival." (PMID 29495592, 2018). "And in vivo study also pointed out that compared with control group, silencing UCA1 produced a smaller tumor and resulted in a longer survival time in nude mice." (PMID 30518750, 2018). "Similar to TUG1, UCA1 showed an asymmetric distribution between tumor tissues, where the lncRNA is upregulated, and serum exosomes, where it is downregulated." (PMID 30195762, 2018). "The results showed significantly higher-UCA1 expression in GC tissues compared to non-tumor tissues." (PMID 30464170, 2018). "UCA1 ectopic expression promotes cell proliferation as well as tumor progression, migration and drug resistance, which are mediated by distinct mechanisms." (PMID 30349036, 2018). "Compared to the paired non-tumor tissues, 68.3% (41/60) of GC cases showed increased expression of UCA1 (defined as greater than a two-fold increase)." (PMID 30464170, 2018). "The expression of these TFs in CRC tumor tissues and their correlation of expression with UCA1 were investigated in GEO and The Cancer Genome Atlas (TCGA) datasets." (PMID 30195762, 2018). "The data indicated that UCA1 potentially contributes to the tumor metastasis of hepatic and pulmonary tissues during EMT of GC cells." (PMID 30464170, 2018). "The results showed that knockdown of UCA1 inhibited tumor growth when compared with the control group." (PMID 29516678, 2018). "Knockdown of CCAT2, FOXCUT, HOTAIR, TUG1 and UCA1 can suppress various aspects of tumor progression." (PMID 29416703, 2018).
tumor (continued). "And then, we detected that expression level of ZEB2, a transcription factor related to tumor metastasis, was regulated by UCA1 in GC cells." (PMID 30464170, 2018). "Quantitative RT-PCR analyses of UCA1 expression were performed in isolated tumor tissues, showing that UCA1 expression in tissues formed from UCA1 silenced cells were lower than those of tumors formed by the blank and negative cells." (PMID 29212166, 2017). "The expression of UCA1 in tumor tissue samples and its paired neighboring histological normal bile duct tissues of 68 patients with CCA was detected by qRT-PCR." (PMID 29221199, 2017). "The results showed that the expression level of UCA1 was remarkably increased in 22 of 30 OSCC patients (73.3%) tumor tissues compared with their normal counterparts." (PMID 29125238, 2017). "Nevertheless, the depth of primary tumor invasion has a significant correlation with UCA1 expression (OR: 2.50, 95 % CI: 1.34–4.67, p = 0.004)." (PMID 28380443, 2017). "The upregulation of UCA1 is responsible for tumor cell proliferation by suppressing G0/G1 cell cycle arrest and apoptosis." (PMID 28423704, 2017). "UCA1 has been recently found to be up-regulated in several cancers, contributing to tumor proliferation, apoptosis, metastasis and survival." (PMID 27713161, 2017). "In the clinicopathological studies, 16 researches consisting of 1291 tumor samples with a correlation between clinicopathological features and UCA1 expression were retrieved in OR analysis." (PMID 28423704, 2017). "The expression of UCA1 was significantly correlated with tumor stage (P = 0.007), lymph node invasion (P = 0.027), TNM stage (P = 0.004) and postoperative recurrence (P = 0.033)." (PMID 29221199, 2017). "Our previous studies have also reported that UCA1 was significantly differentially expressed in gastric cancer tumor tissues and their paired adjacent non-tumor tissues." (PMID 29212166, 2017). "The OSCC nude mice model experiments demonstrated that depletion of UCA1 further boosted CDDP‐mediated repression effect on tumor growth." (PMID 29125238, 2017). "siRNA knockdown of UCA1 re-sensitized tumour cells to gefitinib in vitro and in vivo and inhibited EMT and AKT/mTOR pathway signalling activation." (PMID 28430163, 2017). "One of major limitations of this study is that our findings were observed for UCA1 in FaDu cells only, while it would be advantageous if the effect of more than one lncRNA is assessed in the both tumor samples and more than one cell line model." (PMID 28327194, 2017). "Meanwhile, total 16 available clinicopathological studies containing 1291 tissue samples were collected to analyze the correlation between UCA1 level and clinicopathological data (clinical stage, tumor size, lymphatic and distant metastasis) shown in." (PMID 28423704, 2017). "In this study, RT‐ qPCR assays revealed that expression levels of UCA1 in OSCC tumor tissues and cells were significantly upregulated compared with normal tissues and cells." (PMID 29125238, 2017). "UCA1 is upregulated in the tumours of NSCLC patients with acquired resistance to the EGFR-TKI gefitinib, but lacking the T790M mutation, compared to levels prior to gefitinib treatment." (PMID 28430163, 2017). "The result revealed that patients with high UCA1 expression in tumor tissues were more prone to LNM." (PMID 27713161, 2017). "In the TCGA data (set 2), a slight (1.5-fold in median expression), but statistically significant (p = 0.026) increase in UCA1 expression in tumour tissues was observed." (PMID 28430799, 2017). "MALAT1, CCAT1, H19, and UCA1 are reported to be oncogenic and associated with worse outcome; MEG3, TUG1 BANCR, and GAS5 are tumor-suppressive and associated with better outcome in lung adenocarcinoma." (PMID 29137177, 2017). "miR-184 is a well-known tumor suppressor in a variety of cancers, and its seed sequence was identified as complementary to the UCA1 mRNA sequence at multiple sites." (PMID 28209917, 2017).
tumor (continued). "Through validation experiments for microarray results, upregulation of UCA1 in HSCC tumor tissues was confirmed." (PMID 28327194, 2017). "In UC tumour tissues, we found a moderate increase of UCA1 expression, which in the TCGA set (set 2) resulted mainly from high expression levels in papillary tumours." (PMID 28430799, 2017). "For instance, up-regulation of a lncRNA urithelial carcinoma-associated 1 (UCA1) in HCC tissues has been closely linked to tumour size, invasion and tumour progression." (PMID 29061150, 2017). "Concurringly, a follow-up study on UCA1 as a urinary biomarker found UCA1 urine analysis to be particularly efficient for detection of pT1 tumours." (PMID 28430799, 2017). "All these data suggested that knockdown of UCA1 blocked tumor growth and increased CDDP sensitivity in OSCC." (PMID 29125238, 2017). "Recently, many studies reported that the expression of UCA1 was significantly upregulated in tumor tissues from human digestive system, and UCA1 played a crucial role in the tumorigenesis of digestive system malignancies." (PMID 28380443, 2017). "The role of UCA1 in drug resistance is mediated by UCA1 interference with miR27b, miR18a, miR16 and other miRNAs, depending on the tumor cell studied." (PMID 29033906, 2017). "In the present study, we design the experiments to investigate the relative expression of UCA1 in CCA tissues and adjacent non-tumor tissues, and evaluated the correlation of UCA1 with clinicopathological parameters." (PMID 29221199, 2017). "In order to investigate the effect of UCA1 in OSCC, RT‐qPCR assays were carried out to assess the respective expression pattern of UCA1 in 30 cases of OSCC tumor tissues and their corresponding adjacent normal tissues specimens." (PMID 29125238, 2017). "The biological role of UCA1 in tumor proliferation, invasion, tumorigenesis, cell cycle progression and DNA repair were investigated." (PMID 27902466, 2017). "Results from animal studies showed that UCA1 had the ability of tumorigenicity using Hep3B cells injection although we failed in finding any correlation between UCA1 expression and tumour size or survival in specimens." (PMID 27009634, 2016). "Of the cancer types used in our microarray experiments, UCA1 showed its oncogenic potential in gastric, colon and lung but had expression characteristic of tumor suppressor in liver." (PMID 26812883, 2016). "Recently, Ni and colleagues reported that the expression of UCA1 was statistically correlated with lymph node metastasis, distant metastasis and tumor stage." (PMID 27148353, 2016). "Collectively, these data indicated that the tumor-promoting role of the miR-204-5p target genes is controlled by UCA1." (PMID 27046651, 2016). "UCA1 not only identified as differentially expressed in tumor tissues (Tumor vs. Normal) but also promoted tumor growth (T3+T4 vs. T1+T2), suggesting its promotional role in tumorigenesis and growth of muscle-invasive bladder cancer." (PMID 27863388, 2016). "It seemed that HBx knockdown displayed stronger tumour-suppressive effects than that of UCA1 knockdown." (PMID 27009634, 2016). "In CRC tissues, high levels of UCA1 expression are correlated with larger tumor volume, greater invasion depth, less differentiated histology, and shorter survival." (PMID 27686732, 2016). "They demonstrated that patients with high UCA1 expression levels had a larger tumor size, less differentiated histology and greater tumor depth as compared to the low UCA1 expression group." (PMID 27148353, 2016). "For example, urothelial carcinoma-associated 1 (UCA1) can directly bind to miR-216b, and the abnormal expression of UCA1 in HCC is correlated with tumor-node-metastasis (TNM) stage and metastasis." (PMID 27672656, 2016). "In vivo, we also found that gefitinib in combination with si-UCA1 inhibited tumor growth in gefitinib-resistant PC9/R model." (PMID 26160838, 2015).
tumor (continued). "During the whole tumor growth period, tumors from the miR-216b and pcDNA/UCA1 co-transfected SMMC7721 cells grew faster than that of miR-216b transfected ones." (PMID 25760077, 2015). "Although the UCA1 test was particularly efficient in detecting pT1 tumours, the sensitivity for both non-invasive and muscle-invasive tumours was 57%." (PMID 26191476, 2015). "Our data shows that miR-216b, acting as a tumor suppressor gene, inhibits cell proliferation, colony formation and induces G0/G1 cell cycle arrest, whereas, UCA1 can overturn these inhibitory effects of miR-216b on HCC cells." (PMID 25760077, 2015). "In contrast, our results support a tumor suppressor/prosenescence function for UCA1 in primary cells." (PMID 24876127, 2014). "Future therapies might include miRNA mimics or inhibitors to restore a youthful, tumor-suppressive miRNA environment, or antisense oligonucleotides (ASOs) targeting oncogenic lncRNAs like UCA1 and HOTAIR." (PMID 40918525, 2025). "Similarly, upregulated Urothelial Cancer Associated 1 (UCA1) was also observed to be increased after HBx in HBV-associated HCC, and promotes tumor growth and metastasis via recruiting EZH2 and repressing p27Kip1/CDK2 signaling in patients with chronic HBV." (PMID 40625740, 2025). "Furthermore, UCA1 modulates drug resistance partly through the miR‐18a‐HIF1α feedback loop, further enhancing hypoxia‐induced tumor survival and metabolic adaptation." (PMID 41031251, 2025). "It is interesting to note that some lncRNAs such as HOTAIR, ANRIL, GAS5, NEAT1, CCAT2, UCA1 are consistently reported to be associated with several prognostic indicators such as advanced FIGO stage, increased tumour growth, lymph node metastasis and lowered survival measures." (PMID 39912983, 2025). "It drives tumor progression through multiple mechanisms: UCA1 can act as a molecular sponge for tumor-suppressive miRNAs, it modulates signaling pathways like mTOR and STAT3 to enhance glycolysis and proliferation, and it interacts with epigenetic regulators to alter gene expression." (PMID 40918525, 2025). "Finally, analysis of BC tissue specimens revealed UCA1 overexpression in all tumor samples compared to healthy samples, contributing to accelerated cancer progression." (PMID 38534790, 2024). "In vivo, UCA1 enhanced both tumor development and DDP resistance in the mice." (PMID 38534790, 2024). "In vivo, UCA1 knockdown increased the apoptosis and reduced the tumor volume in the mice." (PMID 38534790, 2024). "Additionally, by competing with the cyclin-dependent kinase inhibitor protein p27, UCA1 promotes tumor development in MCF7 cells." (PMID 38534790, 2024). "The in vivo experiment revealed significant tumor suppression following the UCA1 knockdown." (PMID 38534790, 2024). "In vivo models were established to determine the role of UCA1 in tumor growth in mice." (PMID 37564930, 2023). "UCA1 was shown to contribute to tumor resistance to cisplatin through the UCA1/miR-143/FOSL2 axis." (PMID 38132461, 2023). "Similarly, lncRNA UCA1 contributes to tumor growth by triggering the M2 polarization of TAMs while decreasing the infiltration of M1 cells." (PMID 37637063, 2023). "This function of UCA1 was consistent with that reported in previous studies of UCA1-induced cellular adaptation and survival, including proerythroblast differentiation, adaptation to a toxic environment, and tumor progression." (PMID 36160709, 2022). "Silencing of UCA1 inhibited PCa cell proliferation, migration and invasion and promoted chemo-sensitivity in vitro and tumour growth in vivo.In addition, UCA1 sponges tumour-suppressive, anti-proliferative miR-143, leading to derepression of its oncogenic target, MYO6 in PCa." (PMID 35159022, 2022). "Overexpression of FTL, GPX4 and NUPR1 in UCA1+ EPCAM+ cells suggests these key genes may be upregulated further along the RMC oncogenic program to increase protection of the tumor against cell death induced by ferroptosis." (PMID 35837094, 2022).
tumor (continued). "Overall, these findings demonstrated that hypoxic exosomal UCA1 may enhance angiogenesis and tumor growth in PC via the miR-96-5p/AMOTL2/ERK1/2 axis and so could be a novel therapeutic target for PC." (PMID 36591473, 2022). "Furthermore, hypoxic exosomal UCA1 increased the proliferation of cancer cells, as well as angiogenesis and tumor growth in a mouse xenograft model." (PMID 36591473, 2022). "Previous study revealed that lncRNA UCA1 was a prognostic biomarker, and it could accelerate tumor proliferation and migration." (PMID 36268280, 2022). "Another lncRNA, UCA1, has an important role in anti-tumor drug resistance." (PMID 35402492, 2022). "Additionally, elevated UCA1 promotes tumor EMT progression and tumor invasion through the miR-143/HMGB1/UCA1 pathway (Table A1)." (PMID 36139386, 2022). "Notably, the expression of lncRNA UCA1 is dysregulated in many malignant tumors, which affects tumor occurrence and development." (PMID 34868904, 2021). "These outcomes suggest that UCA1 might play a crucial role in promoting the tumor growth of the GC in vivo." (PMID 34238213, 2021). "Moreover, the upregulated expression of several lncRNAs, such as LINC00152, MALAT1, PVT1, UCA1, etc are also correlated with poor prognosis, tumor progression, lymph node invasion, and TNM stage advancement." (PMID 34944491, 2021). "Higher expression of UCA1 was related to tumor size and lymph node invasion." (PMID 33954114, 2021). "Similarly, it has also been discovered that lncRNA UCA1 is overexpressed in both GC tumor and cell lines." (PMID 33936199, 2021). "The UCA1 expression level was confirmed by Q-PCR assay using xenograft tumor tissues." (PMID 34238213, 2021). "Additionally, lncRNA UCA1 also can directly interact with miR-204 to reduce miR-204-mediated Sox4 degradation; thus, Sox4 can exert its biological role as a tumor-promoting protein to stimulate EC progression." (PMID 33936199, 2021). "UCA1 promotes cell proliferation, tumor progression, migration and drug resistance." (PMID 34055770, 2021). "In tumor tissue injected subcutaneously in mice, the UCA1 overexpression also correlated with immunohistochemical expression of Ki-67, indicating that UCA1 may participate actively in proliferation and tumor growth processes." (PMID 34575316, 2021). "Therefore, in vivo experiments are needed to test the roles of the interaction between UCA1 and WT1-AS in tumor progression as well as the potential reasons underlying the lower levels of WT1-AS in NSCLC relative to normal lung." (PMID 33514344, 2021). "Additionally, UCA1 enhanced the expression of tumor inducer iASSP expression via inhibiting miR-182 expression." (PMID 34322395, 2021). "In PC, hypoxic exosome-mediated UCA1 could promote tumor angiogenesis and accelerate tumor growth via the miR-96-5P/AMOTL2/ERK1/2 axis and serve as a novel therapeutic target." (PMID 34124046, 2021). "Moreover, researchers have demonstrated that UCA1 acts as a driver of tumor progression and drug resistance in many cancers." (PMID 33565716, 2021). "The interplay of CRC tumor microenvironment on the expression of lncRNA UCA1 has also been studied." (PMID 33936199, 2021). "Especially in CRC, increased UCA1 correlated with tumor proliferation and metastasis, and could be used as a predictor for patients’ poor prognosis." (PMID 32246818, 2020). "UCA1 was found to be a very sensitive and specific tumor-specific marker." (PMID 33680939, 2020). "As for the asymmetric distribution of UCA1, it is hypothesized that tumor cells limit the secretion of UCA1 via exosomes to retain UCA1, which suggests that it has a crucial oncogenic function in CRC progression." (PMID 32092975, 2020). "The key finding of the present study is that GAS8-AS1 is downregulated in OS and may play a role as tumor suppressor in OS by downregulating lncRNA UCA1, which promotes OS progression." (PMID 32013985, 2020). "The role of UCA1 as a miRNA sponge in neoplasms has been reported in several studies." (PMID 31996265, 2020).